SPHK2 (sphingosine kinase 2)
Description:
Catalyzes the phosphorylation of sphingosine to form sphingosine-1-phosphate (SPP), a lipid mediator with both intra- and extracellular functions. Also acts on D-erythro-dihydrosphingosine, D-erythro-sphingosine and L-threo-dihydrosphingosine. Binds phosphoinositides. In contrast to prosurvival SPHK1, has a positive effect on intracellular ceramide levels, inhibits cells growth and enhances apoptosis. In mitochondria, is important for cytochrome-c oxidase assembly and mitochondrial respiration. The SPP produced in mitochondria binds PHB2 and modulates the regulation via PHB2 of complex IV assembly and respiration. In nucleus, plays a role in epigenetic regulation of gene expression. Interacts with HDAC1 and HDAC2 and, through SPP production, inhibits their enzymatic activity, preventing the removal of acetyl groups from lysine residues with histones. Up-regulates acetylation of histone H3-K9, histone H4-K5 and histone H2B-K12. In nucleus, may have an inhibitory effect on DNA synthesis and cell cycle. In mast cells, is the main regulator of SPP production which mediates calcium influx, NF-kappa-B activation, cytokine production, such as TNF and IL6, and degranulation of mast cells (By similarity). In dopaminergic neurons, is involved in promoting mitochondrial functions regulating ATP and ROS levels (By similarity). Also involved in the regulation of glucose and lipid metabolism (By similarity).
Synonyms: SK 2; SPK 2; SK-2; SPK-2
Tractability: Small molecule: a drug acting on it is in phase 2 or 3 trials; a high-quality ligand is known. PROTAC: its protein half-life has been measured; a small molecule that binds it is known.
Target class: Enzyme
Gene: Protein-coding gene on chromosome 19 (48,619,291 to 48,630,717, forward strand). Ensembl gene ENSG00000063176.
Subcellular location: Cytoplasm; Nucleus; Endoplasmic reticulum; Mitochondrion inner membrane; Lysosome membrane (Isoform 2)
Subcellular location (Human Protein Atlas): Nucleoplasm
Pathways (Reactome):
Metabolism: Sphingolipid de novo biosynthesis
Gene Ontology:
Molecular function: histone binding; protein binding; sphingosine kinase activity; sphingosine-1-phosphate receptor activity; lipid kinase activity; small GTPase binding; kinase activity
Biological process: cellular response to phorbol 13-acetate 12-myristate; positive regulation of apoptotic process; positive regulation of ceramide biosynthetic process; regulation of cytochrome-c oxidase activity; sphinganine-1-phosphate biosynthetic process; sphingosine biosynthetic process; transcription initiation-coupled chromatin remodeling; intracellular signal transduction; negative regulation of cell growth; positive regulation of cytokine production involved in immune response; positive regulation of interleukin-13 production; positive regulation of interleukin-6 production; positive regulation of mast cell activation involved in immune response; positive regulation of mast cell degranulation; positive regulation of tumor necrosis factor production; regulation of ATP biosynthetic process; regulation of canonical NF-kappaB signal transduction; regulation of reactive oxygen species biosynthetic process; sphingolipid biosynthetic process; sphingosine metabolic process; female pregnancy; regulation of apoptotic process; regulation of lipid metabolic process; regulation of transport; sphingosine-1-phosphate receptor signaling pathway
Cellular component: cytoplasm; cytosol; lysosomal membrane; membrane; nucleoplasm; nucleosome; nucleus; endoplasmic reticulum; mitochondrial inner membrane; mitochondrion; plasma membrane
Genetic constraint (gnomAD): Loss-of-function variants: 22 observed, 33.63 expected, observed/expected ratio (o/e) 0.65, 90% interval 0.47 to 0.93. The upper end of that interval is the gene's LOEUF score, 0.93, which puts it in group 3 of 6, group 1 being the genes least tolerant of losing a copy. Missense variants: 850 observed, 893.17 expected, observed/expected ratio (o/e) 0.95, 90% interval 0.9 to 1.01. Synonymous variants: 462 observed, 413.25 expected, observed/expected ratio (o/e) 1.12, 90% interval 1.03 to 1.21.
Homologues: Orthologues: macaque SPHK2 (95% identical), pig SPHK2 (93% identical), dog SPHK2 (91% identical), guinea pig SPHK2 (82% identical), rat Sphk2 (79% identical), mouse Sphk2 (79% identical), zebrafish sphk2 (51% identical), tropical clawed frog sphk2 (48% identical), chimpanzee SPHK2 (39% identical), Drosophila melanogaster Sk1 (29% identical), Drosophila melanogaster Sk2 (28% identical), Caenorhabditis elegans sphk-1 (19% identical), and 2 more. Paralogues in human: SPHK1 (29% identical), CERK (17% identical), CERKL (15% identical), AGK (12% identical).
Diseases named in the same sentence as SPHK2 in open-access papers:
SPHK2 is named in the same sentence as 153 diseases in open-access papers, as found by Europe PMC text mining. Sharing a sentence is not in itself a finding about the gene and the disease. The quoted sentences say what the papers report.
breast carcinoma (29 papers, 2011 to 2026). "Sphk2-deficient MCF-7 breast cancer cells grow poorly in vivo." (PMID 26956050, 2016). "A previous study in the Michigan Cancer Foundation-7 (MCF-7) breast cancer cell line showed phorbol myristate acetate-induced translocation of SPHK2 to the nucleus and generation of nuclear S1P, which inhibited HDAC activity." (PMID 33802941, 2021). "On reaching the nucleus of a breast cancer cell, it is phosphorylated by SphK2, inhibiting histone deacetylases." (PMID 33758708, 2021). "Of interest, SPHK2 expression, and subsequent S1P production, in human breast cancer MCF7 cells has been shown to direct macrophage polarization to a pro-tumorigenic, and anti-inflammatory state, in vivo and in vitro." (PMID 32708944, 2020). "Significantly increased SphK2 expression levels were also observed in chemoresistant breast cancer cells." (PMID 32670862, 2020). "In our previous studies, we confirmed that increased phospho-Sphk1 or phospho-SphK2 was correlated with the increased S1P in breast cancer cells." (PMID 32796926, 2020). "Our group was the first to demonstrate the mechanism of how S1P is generated inside a breast cancer cell by SphK1, where SphK2 is often suppressed in a compensatory manner, and is then exported out of breast cancer cells by transporters including SPNS2." (PMID 32933189, 2020). "This is consistent with our previous report showing that both SphK1 and SphK2 are important for insulin-induced growth in breast cancer cells." (PMID 32796926, 2020). "For instance, SphK2 isoform activation promoted actin rearrangement into membrane ruffles/lamellipodia in response to S1P in MCF-7 breast cancer cells." (PMID 29385066, 2018). "Inhibition of Sphk2 has been shown to synergize with chemotherapeutic agents in breast cancer cell lines." (PMID 26956050, 2016). "Following treatment with FTY720, an analog of sphingosine, FTY720-P is produced and accumulates over time in the nucleus of human and murine breast cancer cells in agreement with the predominant nuclear localization of SphK2 in these cells." (PMID 26053034, 2015). "We found that FTY720 is phosphorylated in breast cancer cells by nuclear sphingosine kinase 2 and accumulates there." (PMID 26053034, 2015). "Recently, interaction between SphK2/S1P and histone deacetylases in breast cancer cells and S1P as a missing co-factor for E3 ubiquitin ligase TRAF2 in HEK 293 cells were shown." (PMID 21304987, 2011). "A remarkable finding is that SPHK1 and SPHK2 expression among the different breast cancer subtypes is highly variable, making it difficult to generalize about the implication of these enzymes in breast cancer." (PMID 35004331, 2021). "Interestingly, SphK1 and SphK2 appear to have opposite effects in cancer: SphK1 is considered pro-oncogenic in breast cancers, while SphK2 was shown to facilitate antiproliferative signaling." (PMID 33919234, 2021). "But in contrast, in breast cancer SPHK2 is required for EGF-directed cell movement." (PMID 31455837, 2020). "Notably, both SphK isoenzymes were equally responsible for insulin-induced cell cycle progression and the proliferation of MCF-7 breast cancer cells, although SphK1 and SphK2 had different roles in mediating insulin-induced ERK1/2 and Akt activation." (PMID 29385066, 2018). "However, in breast cancer cells, studies have shown an upregulation of SphK1/SphK2." (PMID 33758708, 2021). "However, the fate of p21 expression as a result of SphK2 inhibition may be cell type specific since it is reported that SphK2 siRNA decreases p21 expression in MCF7 breast cancer cells." (PMID 27517489, 2016).
breast carcinoma (continued). "However, it was subsequently shown that downregulation of SphK2 inhibits the proliferation and migration of tumor cells, such as glioblastoma and breast cancer cells and ablation of SphK2 or employing a SphK2 inhibitor has been shown to inhibit the xenograft growth of tumor cells in mice." (PMID 23437140, 2013). "Our reanalysis of a published microarray dataset showed that compared to other subtypes of breast cancer, TNBC patient samples exhibited elevated mRNA expression levels of SPHK1 yet the decreased expression of SPHK2." (PMID 37048053, 2023). "Downregulation of SphK2 by small interfering RNA also reduced migration of T24 human bladder carcinoma, MDA-MB-231 breast cancer, and A-498 kidney carcinoma cells." (PMID 27800303, 2016). "Moreover, a study in breast cancer cells has shown that insulin can also mediate mitogenic effects via both SPHK1 and SPHK2." (PMID 36979912, 2023). "Given the importance of PAK1 and LIMK1 in breast cancer metastasis, we examined whether the PAK1/LIMK1/Cofilin1 signaling pathway is the downstream signaling cascade of SphK2/S1P." (PMID 33968977, 2021). "To investigate whether the SPHK-S1P axis is altered in breast CSCs, we evaluated the basal expression levels of SPHK1, phosphorylated SPHK1, and SPHK2 in a panel of breast CSCs derived from MCF-7, SKBR3, MDA-MB-468, and HCC38 breast cancer cells." (PMID 32260399, 2020). "Together, these results indicate that breast cancer cells take up FTY720 and that FTY720-P produced in the nucleus by SphK2 inhibits class I HDACs and increases specific histone acetylations and regulates expression of a restricted subset of gene programs independently of S1PRs." (PMID 26053034, 2015). "This provides further evidence that SPHK2 is not likely to have significant effects on growth and survival of breast cancer cells." (PMID 25153718, 2014). "Results showed that SPHK2 siRNA knockdown in breast cancer cell did not affect colony formation and cell proliferation." (PMID 25153718, 2014). "Furthermore, treatment of chemo and hormone therapy-resistant breast cancer with the SPHK2 inhibitor ABC294640 completely inhibited tumor volume, suggesting that pharmacological inhibition of SPHK2 could be a strong anti-cancer strategy." (PMID 31817453, 2019). "Interestingly, in breast cancer MCF-7 cells, SphK2, but not SphK1, was associated with histone H3 and on stimulation with phorbol ester produced S1P." (PMID 23028939, 2012). "On the other hand, knockdown of SphK2, but not SphK1, in U1242 and U87 MG glioblastoma cells attenuated cell proliferation and doxorubicin-induced apoptosis in MCF7 breast cancer cells." (PMID 23028939, 2012).
colon carcinoma (18 papers, 2011 to 2024). "Recently, we reported that overexpression of SphK2 correlated to the loss of RARβ and RXRα in colonic cancer cells." (PMID 28465486, 2017). "On the other hand, loss of SPHK2 in haematopoietic cells had a tumour-promoting effect in a colitis associated colon cancer model." (PMID 24970218, 2014). "Furthermore, SPHK2 overexpression and a change in the cellular metabolic flux are important players in inflammation-associated colon cancer in UC." (PMID 37298127, 2023). "Furthermore, the overexpression of SPHK2 and a shift of metabolites involved in energy metabolism (the Warburg effect) are important players in inflammation-associated colon cancer progression in the sigmoid colon of UC." (PMID 37298127, 2023). "In addition, SphK2 has been implicated in chemotherapeutic drug doxorubicin-mediated apoptosis in HCT116 colon carcinoma cells, increasing its effect by down-regulation of SphK2 with specific siRNA." (PMID 34357010, 2021). "It has previously been shown that BRAF mutated RKO colon cancer cells have remarkably higher activities and protein expression levels of SphK1 and SphK2 in comparison to several other colon cancer cell lines harbouring wild-type BRAF, and that they exhibit the least sensitivity to oxaliplatin." (PMID 34639107, 2021). "The effects of glucose deprivation and hypoxia in colon cancer cells could be associated with a specific regulation of SphK2 expression which was attenuated under these stress conditions." (PMID 32456134, 2020). "Altogether, the obtained data point to the relevance of S1P metabolism in the development of resistance to vemurafenib and indicate that targeting S1P production by the SphK2 inhibitor ABC294640 could increase the sensitivity of BRAF mutated resistant colon cancer cells to vemurafenib." (PMID 34639107, 2021). "On the contrary, high expression of SphK2 has been reported in other cancer types, including breast, lung, and colon cancers." (PMID 35494957, 2022). "ABC294640 (3-(4-chlorophenyl)-N-(4-pyridinylmethyl)-tricyclo (3.3.1.13,7) decane-1-carboxamide), a first-in-class sphingosine kinase 2 (SphK2) inhibitor undergoing clinical trials, has shown promising results in reversing chemoresistance in colon cancer." (PMID 34639107, 2021). "Knockdown of SphK2 expression by siRNA curtailed proliferative capability of colon cancer LoVo cells and inhibited their migratory and invasion potential suggesting that SphK2 confers malignant phenotype of colon cancer cells." (PMID 32456134, 2020). "Transcription factor CREB, whose activation was preceded by JNK activation, was identified as the major inducer of SphK2 transcription under serum deprivation conditions in colon cancer cells." (PMID 32456134, 2020). "The activation of JNK followed by CREB as shown in our study was previously reported to be important in enhancing the transcription of sphingosine kinase 2 (SPHK2), which is elevated in colon cancer." (PMID 30222739, 2018). "In the current study, we showed that SphK2 expression level was inconsistent in different primary colon cancer cells, which negatively correlated to ABC294640’s sensitivity." (PMID 26337959, 2015). "Our results demonstrate for the first time that luteolin can act as inhibitor of SphK2, the predominant SphK isoform in the used CC cell line, as well as in several colon cancer cell lines, but exerts only a modest, if any, effect on SphK1 activity." (PMID 26580959, 2015). "In this regard, downregulation of SPHK2 in breast and colon cancer cell lines reduced induction of the cell cycle inhibitor p21 and sensitized the cells to apoptosis induced with doxorubicin." (PMID 24970218, 2014). "Higher activity of SphK1 and SphK2 in oxaliplatin-resistant colon cancer cell line RKO and knockdown of either SphK1 or SphK2 abrogates RKO cells oxaliplatin resistance." (PMID 21490804, 2011).
colon carcinoma (continued). "Interestingly, as previously reported in all-trans retinoic acid-resistant colon cancer cells, SphK2 overexpression resulted in the downregulation of endogenous RXRα, but not of LXRα/β." (PMID 38280459, 2024). "Interestingly, it seems that what lay behind the unresponsiveness to ATRA was high expression of SphK2, since the response of colon cancer cells to ATRA was enhanced when SphK2 was knocked down by siRNA." (PMID 32456134, 2020). "Overexpression of Spns2 is believed to initiate compensatory mechanism by which colon cancer cells restore S1P levels by upregulating SphK1 and SphK2 and activate ERK and AKT signaling pathways that are by all means important for cell survival and cancer progression." (PMID 32456134, 2020). "Indeed, sphingosine kinase 2 (SphK2) over-expression was found in colonic cancer cells resistant to retinoic acids." (PMID 32012980, 2020). "Additional studies conducted using SPHK2-siRNA indicate that decreased expression of SPHK2 enhanced apoptosis and decreased resistance to etoposide and doxorubicin in cell lines derived from lung, breast, and colon tumors." (PMID 31891125, 2018). "Here we show that SphK2 overexpression contributes to the resistance of all-trans retinoic acid (ATRA) therapy in colon cancer through rapid degradation of cytoplasmic retinoid X receptor α (RXRα) by lysine 48 (K48)- and lysine 63 (K63)-based polyubiquitination." (PMID 28465486, 2017). "Inhibition of Sphk2 is observed to suppress colitis-driven colon cancer in mice." (PMID 26956050, 2016). "Moreover, oral administration of ABC294640 supressed HT-29 xenografts growth in nude mice, which puts forward that targeting sphingosine kinase 2 by ABC294640 could provide a novel therapeutic opportunity for BRAF mutant colon cancer." (PMID 34639107, 2021). "Thus, SphK2 seems to play different roles in colon cancer cells under different stress conditions." (PMID 32456134, 2020). "In spite the role of SphK2 in colon cancer remains unclear, this isoform was shown to contribute to oxaliplatin resistance in human colon cancer cells, and its inhibition by sodium butyrate results in colon cancer cell apoptosis." (PMID 26580959, 2015). "It has been shown that down-regulation of sphingosine kinase 2 increases ATRA-induced RARβ expression, arrests the cell cycle in G1 phase, and induces apoptosis in colon cancer cells." (PMID 36135086, 2022). "As expected, the treatment of RKO cells with a dual SphK1/SphK2 inhibitor significantly increased cytotoxic effects of oxaliplatin, which suggests that SphK1 and SphK2 regulate chemosensitivity of BRAF mutant colon cancer cells." (PMID 34639107, 2021). "Treatment of colon cancer cells with NaBT activates PKD that induces the activity of SphK2 and stimulates its translocation from the nucleus into the cytosol where SphK2 accumulates and inhibits NaBT-induced apoptosis." (PMID 32456134, 2020). "In addition, S1P antagonized the effects of ATRA on colon cancer cell proliferation, ATRA-stimulated RARβ expression, G1 phase arrest and apoptosis induction, and these events were reversed by down-regulation of SphK2." (PMID 32456134, 2020). "Study in colon cancer cells has indicated that specific stress stimuli such as serum deprivation increases mRNA, protein and enzyme activity of SphK2 but not SphK1." (PMID 32456134, 2020). "Studies using genetic knockdown of SphK1 and SphK2 in mouse colon cancer models revealed SphK1−/− mice were significantly protected against colon cancer whereas this protection was not evident in SphK2−/− mouse models." (PMID 28415564, 2017). "Findings from these studies indicate that S1P/SphK2 may play a protective role against cytotoxic effects of ATRA in colon cancer cells and encourage further studies into targeting this signaling axis to improve therapeutic efficacy of retinoids in colon cancer treatment." (PMID 32456134, 2020).